BRAF (B-Raf proto-oncogene, serine/threonine kinase)
Diseases named in the same sentence as BRAF in open-access papers (continued):
Sharing a sentence is not in itself a finding about the gene and the disease.
tumor (continued). "According to a recent study, BRAF V600E in BRAF V600E mutant TC inhibits tumor cell death by regulating mitochondrial permeability transition through the pERK-pGSK-CypD signaling axis." (PMID 41008599, 2025). "In the multivariable model, patients with BRAF-V600Emt tumours demonstrated a worse OS than patients with RASmt and RAS&BRAFwt tumours." (PMID 40437037, 2025). "Insights from The Cancer Genome Atlas (TCGA) and transcriptomic scoring systems (e.g., BRAF–RAS score) now link genotype to tumor morphology, metastatic tropism, and radioactive iodine refractoriness." (PMID 41595456, 2025). "Although BRAF inhibitors such as vemurafenib can initially induce ferroptosis-like cell death through lipid peroxidation, tumor cells often adapt by upregulating antioxidant defenses, particularly the SLC7A11–GPX4 axis." (PMID 40909289, 2025). "Our method can not only uncover disease-causing genes with abnormal expression in tumor samples such as CD74, HGF, but it can also identify genes with stable expression yet crucial roles in LUSC, such as BRAF, KDM6A, MAP2K1, and TPR." (PMID 40136480, 2025). "We next examined the protein levels of c-Myc, TERT, BRAF and PP2Ac in tumor tissues using IHC assays." (PMID 40860184, 2025). "IHC analysis of clinical human BRAFV600E PTC and corresponding BRAFWT-PTC samples revealed that EGER is highly expressed in BRAF-mutant tumor tissue." (PMID 39744439, 2025). "Recently, BRAF inhibitors have received approval based on organ-specific studies and basket trials, and even on a tumor-agnostic basis." (PMID 40332392, 2025). "High-grade tumours were more frequent in right colon than in left colon and rectum, and in BRAF-V600Emt compared with RASmt and RAS&BRAFwt." (PMID 40437037, 2025). "SHAP indicated that maximum tumor diameter, BRAF abundance, age, and microcalcifications contributed most to predictions." (PMID 41228353, 2025). "Given their functional interplay within this pathway, aberrant activation of NRAS and BRAF contributes to sustained mitogenic signaling and tumor progression." (PMID 40427124, 2025). "This reduction led to increased expression of KRAS and downstream effectors ERK1/2 and BRAF, enhancing the viability of tumor cells and promoting metastasis." (PMID 41416095, 2025). "These include NTRK fusions, BRAF V600E mutations, RET fusions, Her-2 positive status, high tumor mutational burden (TMB-H), and deficient mismatch repair/high microsatellite instability (dMMR/MSI-H)." (PMID 40868288, 2025). "In BRAF V600E-mutant CRC, tumor cells often exhibit an initial response to BRAF inhibitors, but frequently develop resistance through reactivation of the MAPK pathway, commonly via KRAS amplification or MEK mutations." (PMID 40783392, 2025). "Among the most clinically relevant mutations, BRAF V600E and TERT promoter mutations are strongly associated with malignancy and aggressive tumor behavior." (PMID 40940948, 2025).
tumor (continued). "Previous studies have demonstrated that BRAF/MEK inhibition with dabrafenib and trametinib in BRAFV600E mutated ATC can result in substantial tumor shrinkage, thereby increasing the likelihood of achieving complete (R0/R1) resections." (PMID 40927298, 2025). "This proportion varied widely according to primary tumour location, mutation status, and MMR-status, being lowest among BRAF-V600Emt and dMMR." (PMID 40437037, 2025). "Decreased KLLN expression results in tumor cell advancement, including potential resistance to BRAF inhibitors." (PMID 40872475, 2025). "Conversely, RAF dimer inhibitor monotherapy (e.g., LY3009120) results in paradoxical ERK activation in BRAF WT tumor cells due to the formation of RAF heterodimers." (PMID 41199020, 2025). "This activation typically results from mutually exclusive mutations in either BRAF or RAS oncogenes, both serving as key drivers of tumour initiation." (PMID 40332222, 2025). "This strengthens the idea that MC4R inhibition is particularly effective in tumor types that rely on ERK1/2 signaling for survival, a pathway highly activated in BRAF-mutated cancers." (PMID 40004697, 2025). "These low-grade lesions, usually managed by surgical excision, arise from paradoxical MAPK activation in RAS-mutant, BRAF–wild-type keratinocytes, representing an on-target, off-tumor effect of vemurafenib." (PMID 41302945, 2025). "Using the Tumor-Node-Metastasis (TNM) system of cancer staging, pathology demonstrated a pT4aN2aM0, stage IIIC, BRAF wild-type, GNA11 mutated tumor with 3 of 13 lymph nodes showing micro-metastases." (PMID 41030443, 2025). "The dismal prognosis of BRAF-fused midline neoplasms up to the first year of life is remarkable, and their behavior is completely different than in older age groups (5-year OS rates 23%)." (PMID 40361492, 2025). "Patients with BRAF-V600Emt tumours had an inferior OS compared with those that had RASmt or RAS&BRAFwt tumours (mOS 6.9 vs 19.0 vs 24.4 months)." (PMID 40437037, 2025). "Key genetic alterations include mutations in BRAF, NF1, and PTEN, elevated mTOR expression, and specific miRNA profiles, which influence tumour progression and response to therapy." (PMID 40831998, 2025). "Recently, in addition to mechanisms related to genomic or epigenetic abnormalities, the tumor microenvironment also seems to play a role in the mechanisms of resistance to BRAF inhibitors." (PMID 40507830, 2025). "By leveraging analysis of a large, real world circulating tumor DNA (ctDNA) profiling database, we highlight a significant subset of NSCLC patients whose tumors harbored Class II and Class III BRAF mutations." (PMID 41282105, 2025). "Other factors, including genetic mutations (e.g.,BRAF, RAS), tumor microenvironment, and immune evasion mechanisms, likely interactwith these signaling pathways to influence tumor behavior." (PMID 40062974, 2025). "Inspection of variants in genes linked to anti‐EGFR therapy (KRAS, BRAF, NRAS, PTEN and PIK3CA) revealed variability across tumours and fractions." (PMID 40302146, 2025). "Genetic alterations in RAS and BRAF often serve as key drivers, overriding normal regulatory mechanisms and fostering tumor growth." (PMID 40075837, 2025). "Upregulation or activation of COT allows tumor cells to bypass blocked BRAF and to fuel MAPK/ERK pathway cascade, reactivating cell proliferation." (PMID 40872623, 2025). "CDx biomarkers (including BRAF, EGFR, PIK3CA, and RAS mutations) and other tumor profiling biomarkers (including clinically relevant alterations and TMB) were represented in marker positive samples diluted with lineage matched marker negative samples." (PMID 40804002, 2025). "Here, we present the case of a BRAF mutant mCRC, on whom we performed noninvasive therapeutic monitoring by various biomarkers, including circulating tumor (ct) DNA and fragmentomics." (PMID 41245504, 2025).
tumor (continued). "This review provides an overview of the molecular diversity of BRAF alterations, their biological implications across tumor types, and the therapeutic strategies that have emerged in response." (PMID 40332392, 2025). "Patients with BRAF-V600Emt tumours had metastasectomies less often than RASmt and RAS&BRAFwt (15% vs 31% vs 36%, p < 0.001)." (PMID 40437037, 2025). "By targeting the BRAF V600E mutation and blocking the MAPK/ERK signaling pathway, targeted therapy significantly reduces the proliferation of PCP tumor cells, slowing or even halting disease progression." (PMID 40696244, 2025). "Given the poor prognosis typically associated with BRAF-mutated BTC, the initial tumor response in our case is particularly noteworthy." (PMID 40688855, 2025). "Among these, the BRAF V600E mutation, the most frequent genetic alteration in PTC, has been extensively corroborated to correlate with enhanced tumor aggressiveness and increased risk of lymph node metastasis." (PMID 41458539, 2025). "The high variation of BRAF-V600Emt, RASmt, dMMR, and treatment allocation population-based per primary tumour location explain the poor outcome in right-sided cancers." (PMID 40437037, 2025). "Tumor heterogeneity affects the strength of signaling pathways through which each tumor responds and adapts to BRAF and MEKi." (PMID 40872623, 2025). "BRAF mutations per se only exhibited a trend of correlation with poor survival (Log-rank P = 0.1451), but when concurring with TPM the likelihood of tumor-related death increased significantly (Log-rank P = 0.0066) (“Online resource – Figure-2”)." (PMID 40272676, 2025). "This review summarizes the influence of HDACs (Zn2+-dependent HDACs and NAD+-dependent sirtuins) on BRAF-mutant cancers and BRAF inhibitor resistance based on upregulated survival mechanisms and the prevention of tumor cell death." (PMID 39935431, 2025). "Diagnostic tumour material was, whenever sufficient, analysed for RAS, BRAF, and PIK3CA mutations, and MMR-status." (PMID 40437037, 2025). "Earlier studies have revealed that the lack of sustained inhibition of HSP90 is key to anti-BRAF therapy insensitivity in BRAF-mutant tumours." (PMID 40357363, 2025). "BRAF mutations downregulated AXIN2, an important tumor suppressor and regulator of the Wnt/β-catenin signaling pathway in CRC." (PMID 41009348, 2025). "These mutations increase AKT activity, leading to the activation of anti-apoptotic signals and pro-proliferative genes, allowing tumor cells to grow independently of BRAF signaling and resist MAPK pathway inhibition." (PMID 40872623, 2025). "Conversely, a significant association was identified between BRAF V600E mutations and MSI (p = 0.043), reinforcing BRAF’s role as a molecular marker of this tumor subtype." (PMID 40647370, 2025). "For the Patient 1, the primary tumor showed an NRAS p.Q61K mutation with multiple CNVs including an allelic imbalance of chromosome 7p, 8p, 13q, and 17p, while the metastasis had a BRAF p.V600K mutation and allelic imbalances on different chromosomes." (PMID 39912776, 2025). "The percentage of stage III/IV cutaneous tumours that were BRAF tested was 52% (n = 4558/8731), whereas the percentage of stage II and I tumours tested was 26% (n = 4441/16 844) and 3% (n = 1366/52 353), respectively." (PMID 40902091, 2025). "Confirming the snRNA-Seq results, MITF and BRAF showed higher expression levels in the ROIs located in tumour tissues, with MITF showing a bigger difference." (PMID 41168392, 2025). "It uses a novel dose escalation design to investigate the safety, pharmacokinetics, pharmacodynamics, and anti-tumor activity in patients with advanced disease who have progressed on first-line BRAF/MEK inhibitors." (PMID 40564107, 2025).
tumor (continued). "Redifferentiation has been used in patients with BRAF-mutated and RAS-mutated tumours in prospective trials and in the case of patients with RET or NTRK fusions." (PMID 40318680, 2025). "Both ECM‐targeting agents significantly delayed tumor regrowth compared to BRAF/MEKi alone, as defined by the time required for tumors to return to their pre‐treatment volume (≈700 mm3)." (PMID 40847444, 2025). "This compensatory mechanism enables tumor cells to survive and proliferate even in the presence of BRAF inhibitors." (PMID 41255582, 2025). "This distribution is also linked to a greater frequency of BRAF mutations and high microsatellite instability (MSI-high) in female patients, both of which are correlated with increased tumor invasiveness." (PMID 40725273, 2025). "In contrast, infection by pHV LV resulted in identification of 3762 (seven-fold increase) DEG of which 81 oncogenes and 82 tumour suppressor genes, that included MECOM, LMO-2 and BRAF genes previously associated with genotoxicity." (PMID 40664913, 2025). "In contrast, the oncogenic BRAF V600E selectively promotes BRAF V600E-burdened tumor development through the OcT-1-HMGCL-aceto-acetate axis." (PMID 39857793, 2025). "Tumor grade followed a similar trend, with G3 tumors having a significantly higher prevalence of KRAS (p=0.01) and BRAF (p=0.0003) mutations." (PMID 40949797, 2025). "In one of the first reported cases, there was an 85% reduction in the solid portions and 81% reduction in the cystic portions of the tumor following treatment with MEK/BRAF inhibitors." (PMID 40433410, 2025). "Early FDG PET after BRAF inhibitor therapy often reveals rapid decreases in tumor uptake in responders." (PMID 41008677, 2025). "Studies have shown that using combination therapies targeting BRAF/MEK/PI3K will go a long way to overcome tumor resistance mechanisms." (PMID 41009348, 2025). "Recently, a phase 2 trial of patients treated with surgery and BRAF/MEKi demonstrated 91% reduction in residual tumor volume." (PMID 39976897, 2025). "Currently, the most relevant genetic markers used by clinicians for predicting tumour behaviour are TC drivers (BRAF, RAS, or RTK, such as RET or NTRK alterations)." (PMID 40332222, 2025). "NP-based imaging agents, such as Cu-Macrin for positron emission tomography, demonstrate high specificity for macrophage-rich lesions, while NP assays improve capture of circulating tumor DNA, including BRAF V600E." (PMID 41497010, 2025). "The aspects of the effectiveness of BRAF/MEK inhibition in relapsed/refractory MM, and the search for mechanisms of tumor cells acquiring resistance to treatment with BRAF inhibitors, are relevant." (PMID 40943426, 2025). "Clinically, molecular biomarkers—including KRAS/NRAS/BRAF mutations, HER2 amplification, PIK3CA mutations, MSI/MMR status, and the tumor microenvironment—play an important role in therapeutic decision-making." (PMID 40805234, 2025). "The chemotherapy regimen, consisting of mFOLFOX6 plus cetuximab, was selected in consultation with an experienced medical oncologist, considering the tumor's RAS/BRAF wild-type status and the need for a prompt and effective systemic response." (PMID 41332047, 2025). "Thus, the coexistence of a somatic BRAF mutation and tumor dMMR/MSI-H status not only suggests a sporadic origin but may also be a marker for prognostic risk stratification in metastatic CRC, as BRAF-mutated tumors exhibiting MSI-H have been associated with poorer survival in the metastatic setting." (PMID 40362635, 2025). "They include measurement beyond the muscularis propria, MLH1 promoter methylation, tumor budding, coexistent pathology, MMR status, and BRAF V600E mutation." (PMID 41310156, 2025). "Preclinical studies have shown that CDK4/6 inhibitors can overcome resistance to BRAF/MEKi, resulting in sustained tumor regression." (PMID 40872623, 2025).
tumor (continued). "Numerous small molecules and nano-materials capable of inducing the ferroptosis pathway and blocking tumor growth are being studied, also enhancing the effect of immunotherapy or the action of BRAF inhibitors." (PMID 40427437, 2025). "Mutations in canonical oncogenes such as BRAF, KRAS, PIK3CA, and ALK function as dominant molecular drivers, defining biologically distinct tumor subsets characterized by specific therapeutic liabilities." (PMID 41228293, 2025). "In tumor tissue, mutations in genes like KRAS, BRAF, and MYC impact polyamine metabolism, leading to an increase in polyamine content within the tissue." (PMID 40390766, 2025). "In contrast, the persistence of RET S649L and BRAF V600E underscores their potential roles as key drivers in this patient’s tumor evolution." (PMID 40756116, 2025). "Clinical trials show that combined BRAF/MEK inhibition (e.g., dabrafenib + trametinib) leads to rapid tumor regression in BRAF‐mutant ATC, prompting guideline recommendations for immediate molecular or immunohistochemical testing." (PMID 41164799, 2025). "MSI-CRC tumours frequently harbour mutations in tumour suppressor genes such as KRAS and pro-oncogenic genes, including BRAF; the V600E mutation in BRAF in particular is characteristic of sporadic MSI-CRC." (PMID 40647444, 2025). "Demographic, clinical, and molecular data, including age, gender, race, tumor location, cancer stage, and mutation status (KRAS, NRAS, BRAF, POLE, ERBB-2/HER2, microsatellite status), were collected by reviewing electronic medical records." (PMID 40940860, 2025). "Next, we examined the correlation between the maturity of intra-tumor TLS and BRAF mutational status." (PMID 40959083, 2025). "It was shown that right‐sided tumours exhibit lower responsiveness to anti‐EGFR treatment and higher mutation rates in genes like BRAF, PIK3CA, and KRAS, suggesting potential underlying reasons for this association." (PMID 40302146, 2025). "Patterns of CNAs vary with genetic backgrounds, with BRAF/NRAS wild-type tumours showing notable increases." (PMID 40831998, 2025). "This highlights the necessity for more comprehensive genetic profiling of tumours, in particular those with class III BRAF mutations." (PMID 40664146, 2025). "During the PDX transplantation process, only the most adaptable tumor cells survive the engraftment bottleneck, BRAF-mut cells often dominate this selection due to their intrinsic growth signaling." (PMID 40507920, 2025). "A study by Nucera suggested that BRAF V600E mutations and the TME in PTC are associated with the EMT process, which promotes tumor proliferation." (PMID 40490818, 2025). "Hematoxylin and eosin sections were dissected into multiple, spatially distinct regions within each tumor and directly Sanger sequenced for the relevant region of BRAF and either KRAS or NRAS, as appropriate." (PMID 39751654, 2025). "In other tumor types, BRAF-targeted approaches have introduced new therapeutic possibilities, often with favorable efficacy and distinct toxicity profiles compared to conventional chemotherapies." (PMID 40332392, 2025). "Despite extensive studies on genetic alterations (e.g., BRAF and RAS mutations) in THCA, the metabolic reprogramming of immune cells within the tumor microenvironment, particularly macrophages, remains poorly characterized." (PMID 40390766, 2025). "Both cohorts included patients with BRAF wild-type primary tumour, synchronous CRLM, and who had undergone neoadjuvant therapy prior to LT." (PMID 40563695, 2025).